PRMT7 (protein arginine methyltransferase 7)
Diseases named in the same sentence as PRMT7 in open-access papers (continued):
Sharing a sentence is not in itself a finding about the gene and the disease.
melanoma (6 papers, 2022 to 2025). A malignant, usually aggressive tumor composed of atypical, neoplastic melanocytes. "PRMT7 is closely associated with tumor immune cell infiltration; in melanoma, inhibition of PRMT7 increases immune cell infiltration, triggering anti-tumor T cell responses to suppress tumor growth." (PMID 41154773, 2025). "In B16 melanoma cells transfected with PRMT7 small interfering RNA or treated with the PRMT7 small molecular inhibitor, SGC30274, PD-L1 mRNA and protein levels were reduced, and ICI therapy potentiated." (PMID 35493527, 2022). "In PRMT7 knockdown or PRMT7 inhibitor-treated murine melanoma B16 cells, MHC-I gene regulators such as Nlrc5 and its target genes are also up-regulated, similar to the MS023 (PRMT1 inhibitor) group." (PMID 35493527, 2022). "Notably, PRMT7’s expression in melanoma inversely correlates with patient survival, where it modulates immune recognition through histone modification, affecting IFN gene expression and MHC-I levels on tumor cells." (PMID 40869229, 2025). "Finally, in a mouse model of melanoma, inhibition of PRMT7 combined with anti-CTLA-4 and anti-PD-1 treatments led to better suppression of tumor growth." (PMID 40869229, 2025). "PRMT7 inhibition induced viral mimicry and sensitized therapy-resistant B16F10 melanoma tumors to CTLA-4 and PD-1 treatment in vivo." (PMID 36497341, 2022). "On the other hand, inhibition of PRMT7 enhances RIG-I and MDA5 expression via reduction of H4R3me2s repressive histone mark at the promoters, which boosts the expression of downstream targets such as interferon-stimulated genes(ISGs) in melanoma, thus hampering tumor growth." (PMID 37662910, 2023).
non-small cell lung carcinoma (5 papers, 2021 to 2025). A group of at least three distinct histological types of lung cancer, including non-small cell squamous cell carcinoma, adenocarcinoma, and large cell carcinoma. "The interaction of eEF2 with PRMT7 also drives invasion and metastasis in non-small cell lung cancer (NSCLC)." (PMID 39707196, 2024). "The interaction between Hspa5 and EEF2 promotes the overexpression of PRMT7 in non-small cell lung cancer cells, thus regulating cancer cell migration and colony formation." (PMID 34437425, 2021). "In non-small-cell lung cancer, the overexpressed protein arginine methyltransferase 7 (PRMT7) could interact with eEF2, thus promoting the cell metastasis." (PMID 39707196, 2024). "Similar function of PRMT7 has also been reported in human non-small-cell lung cancer (NSCLC)." (PMID 34712331, 2021).
Obesity (5 papers, 2017 to 2023). Accumulation of substantial excess body fat. "Both Prmt7-deficient mice and patients with Prmt7 mutations reportedly exhibit obesity." (PMID 36013373, 2022). "A study on human genetic developmental disorders identified PRMT7 mutations as responsible for a phenotype that phenocopies pseudohypoparathyroidism with mild intellectual disability, obesity, and symmetrical shortening of the digits, posterior metacarpals, and metatarsals." (PMID 34440512, 2021). "The same mice showed a switch from oxidative to glycolytic fibers in muscle before obesity development, suggesting that the consequent imbalance in energy homeostasis might be the cause of the obesity in mice and implying PRMT7 as an important co-factor in adult muscle development." (PMID 36399134, 2023). "We suggest that PRMT7-related disorder should be considered in the differential diagnosis of monogenic syndromic obesity." (PMID 36399134, 2023). "It has only been reported that Col6a3 is associated with cancer, muscular dystrophy, and obesity, which exhibits the possible similar roles of Prmt7." (PMID 36013373, 2022). "PRMT7 was found expressed in brown and white adipose tissues of mouse, and PRMT7−/− mice at middle age developed obesity with excessive body fat accumulation." (PMID 34712331, 2021). "We hereby confirm the importance of PRMT7 function in human adipogenesis, suggesting that it might be a potential target for intervention and treatment of obesity." (PMID 36399134, 2023).
viral infection (5 papers, 2020 to 2024). "Interestingly, the authors show that the loss of one PRMT7 allele protects mice from viral infections." (PMID 34440512, 2021). "Thus, both studies in mice and zebrafish above indicate that PRMT7 confers susceptibility to viral infections and enhances the immune response." (PMID 34440512, 2021). "In early virus infection stages, PRMT7 was auto-methylated at R32, disabling its enzymatic activity and aggregation." (PMID 35493527, 2022). "A recent study in mice also indicates increased resistance to viral infection-induced lethality in PRMT7 knockout animals." (PMID 34440512, 2021). "PRMT7 attenuates the binding of MAVS to TRIM31 and RIG-I by catalyzing the mono-methylation of MAVS at the R52 residue, but aggregated PRMT7 is incapacitated upon viral infection due to auto-methylation at the R32 residue, subsequently alleviating its suppressive effect on MAVS activation." (PMID 38970666, 2024). "Other genes like BTN3A3 (ENSG00000111801), PRMT7 (ENSG00000132600) and COLCA2 (ENSG00000214290) are all proliferation associated genes, which may participate in the repair procedures after lung tissue damage caused by viral infection." (PMID 33505977, 2020).
prostate carcinoma (4 papers, 2021 to 2025). A carcinoma that arises from epithelial cells of the prostate gland. "Aberrant expression of PRMT7 has been linked with altered RNA splicing, proliferation, and colony formation in breast, colorectal, and prostate cancers." (PMID 35565298, 2022). "The critical roles of PRMT4, PRMT5, PRMT7, and hnRNPA1 in cell growth were also demonstrated in HCT 116 cells, a colon cancer cell line, and LNCaP, a prostate cancer cell line." (PMID 33782401, 2021).
renal cell carcinoma (4 papers, 2021 to 2025). "In NSCLC, T-ALL, and renal cell carcinoma, PRMT7’s overexpression is associated with increased invasion and poor prognosis." (PMID 40869229, 2025). "PRMT7 expression was correlated with a poor prognosis in renal cell carcinoma by upregulating c-Myc expression through methylation (and stabilization) of β-catenin." (PMID 40869229, 2025). "Further assays discovered that PRMT7 promoted the proliferation of renal cell carcinoma both in vitro and in vivo." (PMID 34712331, 2021). "Overall, PRMT7 also serves as an oncogene in renal cell carcinoma via the β-catenin/c-Myc pathway." (PMID 34712331, 2021). "Additionally, PRMT7 has been shown to interact with the Beta-catenin-C-Myc axis and promote the growth of renal cell carcinoma (RCC)." (PMID 33440687, 2021).
chronic obstructive pulmonary disease (3 papers, 2022 to 2025). A chronic and progressive lung disorder characterized by the loss of elasticity of the bronchial tree and the air sacs, destruction of the air sacs wall, thickening of the bronchial wall, and mucous accumulation in the bronchial tree. "In chronic obstructive pulmonary disease (COPD), monocytes in lung tissue induce the transcription of PRMT7 through the NF-κB/RelA signaling pathway." (PMID 37699892, 2023). "Therefore, the therapeutic application of bindarit or other PRMT7-targeting strategies in MI should be approached cautiously, especially in patients with comorbidities such as chronic obstructive pulmonary disease, where PRMT7 activation may have pro-inflammatory consequences." (PMID 40764455, 2025). "Here we show that in chronic obstructive pulmonary disease (COPD) patients, PRMT7 expression is elevated in the lung tissue and localized to the macrophages." (PMID 35288557, 2022).
gastric cancer (3 papers, 2023 to 2026). A primary or metastatic malignant neoplasm involving the stomach. "On the other hand, decreased PRMT7 expression is linked to tumorigenesis in liver and gastric cancers, mediated through interactions with miR-24-2 and PTEN, respectively." (PMID 40869229, 2025). "Clinical analysis reveals that elevated GLUD1, PRMT7, and meGLUD1(R76) levels correlate with tumor progression in gastric cancer." (PMID 41876450, 2026). "Protein arginine methyltransferase 7 (PRMT7) plays a crucial role in tumor occurrence and development; however, its expression pattern, biological function, and specific mechanism in gastric cancer (GC) remain poorly defined." (PMID 37781082, 2023).
hepatocellular carcinoma (3 papers, 2022 to 2024). A malignant tumor that arises from hepatocytes. "In hepatocellular carcinoma, an PRMT7 enhancer was found to bind to the transcription factor HNF4A to promote the expression of the host gene PRMT7, which ultimately contributes to HCC pathogenesis." (PMID 38849954, 2024).
Intellectual disability (3 papers, 2019 to 2025). "Notably, patient 8 was found to have biallelic variants in the PRMT7 gene, causing short stature, brachydactyly, intellectual disability, dysmorphic facial features, and seizures syndrome (SBIDDS), which aligns with her clinical presentation." (PMID 40589517, 2025).
leukemia (3 papers, 2022 to 2024). A malignant (clonal) hematologic disorder, involving hematopoietic stem cells and characterized by the presence of primitive or atypical myeloid or lymphoid cells in the bone marrow and the blood. "Mechanistically, PRMT7 loss resulted in reduced expression of glycine decarboxylase, leading to the reprogramed glycine metabolism to generate methylglyoxal, which is detrimental to leukemia stem cells." (PMID 38218942, 2024). "Besides, remodeled glycine metabolism mediated by protein arginine methyltransferase 7 (PRMT7) induces toxic death of leukemia stem cells." (PMID 38218942, 2024). "Therefore, we examined the expression of the PRMT enzymes across hematological malignancies, particularly leukemias, and focused on the role of PRMT7 in T-ALL pathogenesis and prognosis." (PMID 35565298, 2022). "Out of the tested leukemia cell lines, T-ALL-derived cells had the highest level of PRMT7 mRNA by RT-qPCR." (PMID 35565298, 2022). "Previously, no comprehensive studies have been conducted on PRMT7 in leukemia and lymphoma." (PMID 35565298, 2022).
breast tumor (2 papers, 2015 to 2017). "An assessment of 1200 breast tumour samples identified that the chromosomal region containing the PRMT7 gene (16q22) is often associated with metastatic breast tumour samples and also associated with decreased patient survival." (PMID 25605249, 2015). "PRMT7 expression was mainly localized to the cytoplasm of normal breast epithelial cells and breast tumour cells." (PMID 25605249, 2015). "Taken together, this expression data suggest that PRMT7 levels are increased at an early stage in breast tumour development where it plays a role in promoting EMT." (PMID 25605249, 2015). "Our rigorous immunohistochemical study of PRMT7 protein expression is the first to demonstrate that PRMT7 protein expression is significantly increased in primary breast tumours and lymph node metastases compared to normal breast tissues." (PMID 25605249, 2015). "We have shown that PRMT7 is overexpressed in breast tumour tissues and is potentially involved in the progression and metastasis of this devastating disease." (PMID 25605249, 2015). "In total we evaluated the expression of PRMT7 in 244 tissue samples comprising of 24 normal breast tissues, 162 primary breast tumours, 48 lymph node metastases and 10 normal lymph nodes." (PMID 25605249, 2015). "We have shown that a significantly higher number of primary breast tumours and lymph node metastatic disease cases display high expression of PRMT7." (PMID 25605249, 2015). "Two pathologists scored PRMT7 staining intensity and distribution within the epithelial cells of the normal breast tissues and the epithelial-derived breast tumour cells to generate a composite score (intensity score multiplied by distribution score) for each of the tissue samples examined." (PMID 25605249, 2015). "Furthermore, the expression of PRMT7 protein was elevated in lymph node metastases originating from primary breast tumours (composite score of 6.29)." (PMID 25605249, 2015). "The PRMT7 composite scores for breast tumour tissues and metastatic tissues were not significantly different." (PMID 25605249, 2015).
cardiac hypertrophy (2 papers, 2024 to 2025). "The onset of cardiac hypertrophy in female cKO mice at the age of 9–10 months, when reproductive senescence transition occurs, prompted us to investigate the effect of Prmt7 deficiency by employing a surgical menopausal model." (PMID 38486105, 2024). "In our previous study on the role of Prmt7 in cardiac function, we showed that cardiac-specific Prmt7 ablation resulted in cardiac hypertrophy accompanied by fibrosis." (PMID 38486105, 2024). "In addition, PRMT7 overexpression attenuates angiotensin II-induced cardiac hypertrophy, whereas PRMT7 deletion exacerbates it." (PMID 40764455, 2025).
cardiomyopathy (2 papers, 2024 to 2025). A disease of the heart muscle or myocardium proper. "In this study, we found that cardiac-specific Prmt7 deficiency in postmenopausal or ovariectomized mice was associated with oxidative stress, apoptosis, and fibrosis, ultimately leading to severe cardiomyopathy." (PMID 38486105, 2024). "The present study explored the role of Prmt7 in protecting against menopause-associated cardiomyopathy." (PMID 38486105, 2024). "Together, these findings suggest that PRMT7 ablation in ECs exacerbates MI-induced cardiomyopathy by dysregulating gene expression related to angiogenesis, cell proliferation and apoptotic processes." (PMID 40764455, 2025). "Conversely, PRMT7 induction via bindarit treatment enhances cell survival and revascularization, highlighting PRMT7 as a promising therapeutic target for mitigating ischemia-induced cardiomyopathy." (PMID 40764455, 2025). "One interesting aspect of cardiac-specific Prmt7-ablated mice was the sex difference in their cardiomyopathy phenotype and survival." (PMID 38486105, 2024). "Considering that estrogen depletion is a critical contributor to cardiomyopathy in aging females, we investigated the correlation between Prmt7 and estrogen in H9c2 cells with cardiotoxicity." (PMID 38486105, 2024). "This sex difference in the cardiomyopathy phenotype prompted us to question the distinct role of Prmt7 in female-related cardiac function." (PMID 38486105, 2024). "Mice with cardiac-specific Prmt7 ablation (cKO) exhibited sex-specific cardiomyopathy." (PMID 38486105, 2024). "Taken together, our data have implications for understanding the cardioprotective role of Prmt7 in postmenopause-related cardiomyopathy and ultimately allow for the identification of new prognostic indicators or novel therapeutic strategies for the treatment of heart failure." (PMID 38486105, 2024). "Interestingly, during this study, cardiomyopathy resulting from Prmt7 deficiency was found only in young male mice and not in young female mice." (PMID 38486105, 2024). "However, if Prmt7 is depleted after menopause, STAT3 signaling is dysregulated due to decreased negative feedback by Socs3, eventually resulting in more severe cardiomyopathy." (PMID 38486105, 2024).
chronic lung disease (2 papers, 2022 to 2025). According to the definitions of the American and British Thoracic Societies, including pulmonary functional tests, X-rays, and CT scans for items such as fibrosis, bronchiectasis, bullae, emphysema, nodular or lymphomatous abnormalities. "Interestingly, depletion of PRMT7 in mice protected these from multiple animal models of chronic lung disease." (PMID 35288557, 2022).
clear cell renal cell carcinoma (2 papers, 2021 to 2022). "In clear-cell renal cell carcinoma, Prmt7 can maintain β-catenin expression to regulate cell proliferation, which demonstrates the possible role of Prmt7 in regulating the Wnt/β-catenin signaling pathway in cancer." (PMID 36013373, 2022). "There was a close correlation between increased PRMT7 expression and poor prognosis of clear cell renal cell carcinoma." (PMID 34712331, 2021).
cryptorchidism (2 papers, 2019 to 2021). The failure of one or both testes of a male fetus to descend from the abdomen into the scrotum during the late part of pregnancy. "Based on the presence of more epididymal fat in PRMT7−/− mice and cryptorchidism in male patients with PRMT7 mutations, it is expected that PRMT7 may have a function in male reproduction." (PMID 34712331, 2021). "Later, a male child was confirmed as PRMT7 null in function, and the child exhibited severe intellectual disability, seizures, short stature, microcephaly, facial dysmorphism, brachydactyly, and cryptorchidism." (PMID 34712331, 2021).
heart failure (2 papers, 2024 to 2025). Inability of the heart to pump blood at an adequate rate to meet tissue metabolic requirements. "In a recent study, a protein named Prmt7 was found to protect heart cells from heart failure." (PMID 38486105, 2024). "This suggests that Prmt7 could be a potential treatment target for heart failure, especially in women after menopause." (PMID 38486105, 2024). "Furthermore, the role of PRMT7 in other cardiovascular conditions, including heart failure with preserved EF and nonischemic cardiomyopathies, warrants further investigation." (PMID 40764455, 2025).
intellectual disability syndrome (2 papers, 2019 to 2025). "A clinical study in patients with intellectual disability syndrome found that those with PRMT7 mutations showed a short stature and brachydactyly, indicating that PRMT7 may be closely related to bone health." (PMID 40342926, 2025). "PRMT7 has previously been associated with SBIDDS syndrome, an intellectual disability syndrome." (PMID 31579629, 2019).
liver cancer (2 papers, 2021 to 2022). An epithelial or non-epithelial malignant neoplasm that arises from the liver. "In a recent study on the effect of SNPs in liver cancer, the rs73613962 (T > G) site at the Protein Arginine Methyltransferase 7 (PRMT7) gene has allele-specific enhancer activity." (PMID 36249028, 2022).
lymphoma (2 papers, 2020 to 2022). A malignant (clonal) proliferation of B- lymphocytes or T- lymphocytes which involves the lymph nodes, bone marrow and/or extranodal sites. "Our findings of PRMT7 inhibition leading to the sensitization of cells to bortezomib-induced cell death indicate potential therapeutic applications in cancers such as multiple myeloma and some lymphomas." (PMID 32409666, 2020).
pulmonary diseases (2 papers, 2021 to 2022). "Collectively, these findings represent one mechanistic explanation for how PRMT7 regulating AMYFs proliferation and differentiation during lung alveologenesis, and may provide potential clues for the treatment of pulmonary diseases caused by AMYF proliferation and differentiation disorders." (PMID 34497269, 2021). "Authors here show in mouse models of lung disease that PRMT7, a protein arginine methyltransferase, is an important regulator of recruitment and the pro-inflammatory phenotype of macrophages." (PMID 35288557, 2022).
rhabdomyosarcoma (2 papers, 2021 to 2022). A rare aggressive malignant mesenchymal neoplasm arising from skeletal muscle. "The expression of PRMT1, CARM1, PRMT5, PRMT7, PRMT8 and PRMT9 were all elevated in rhabdomyosarcoma, CARM1 and its direct interaction with histone acetyltransferase PCAF jointly were also detected to exert an increased expression of myogenin gene and lead to rhabdomyosarcoma cell differentiation." (PMID 35311114, 2022).